RNU4-8P (RNA, U4 small nuclear 8, pseudogene)
Synonyms: U4; U4/14; LOC124900516; formerly RNU4P2
Gene: Small nuclear RNA gene on chromosome 2 (97,664,591 to 97,664,731, reverse strand). Ensembl gene ENSG00000201806.
Homologues: Orthologues: chimpanzee U4 (98% identical), macaque U4 (94% identical), rat LOC120103371 (60% identical), dog U4 (58% identical), mouse Gm25179 (57% identical), dog U4 (52% identical), dog U4 (50% identical). Paralogues in human: RNU4-7P (86% identical), RNU4-13P (84% identical), RNU4-58P (84% identical), RNU4-67P (84% identical), RNU4-68P (84% identical), RNU4-42P (81% identical), RNU4-76P (81% identical), RNU4-45P (80% identical), RNU4-44P (79% identical), RNU4-16P (79% identical), RNU4-23P (79% identical), RNU4-92P (79% identical), and 81 more.